TXNDC17 (thioredoxin domain containing 17)
Description:
Disulfide reductase. May participate in various redox reactions through the reversible oxidation of its active center dithiol to a disulfide and catalyze dithiol-disulfide exchange reactions. Modulates TNF signaling and NF-kappa-B activation. Has peroxidase activity and may contribute to the elimination of cellular hydrogen peroxide.
Synonyms: TRP14; TXNL5; MGC14353
Tractability: PROTAC: ubiquitination databases record sites on it; its protein half-life has been measured.
Gene: Protein-coding gene on chromosome 17 (6,640,712 to 6,644,541, forward strand). Ensembl gene ENSG00000129235.
Subcellular location: Cytoplasm
Gene Ontology:
Molecular function: protein binding; protein-disulfide reductase [NAD(P)H] activity
Biological process: tumor necrosis factor-mediated signaling pathway
Cellular component: cytoplasm; cytosol; extracellular exosome
Genetic constraint (gnomAD): Loss-of-function variants: 11 observed, 13.17 expected, observed/expected ratio (o/e) 0.84, 90% interval 0.52 to 1.38. The upper end of that interval is the gene's LOEUF score, 1.38, which puts it in group 5 of 6, group 1 being the genes least tolerant of losing a copy. Missense variants: 132 observed, 130.67 expected, observed/expected ratio (o/e) 1.01, 90% interval 0.88 to 1.17. Synonymous variants: 53 observed, 49.21 expected, observed/expected ratio (o/e) 1.08, 90% interval 0.86 to 1.35.
Homologues: Orthologues: chimpanzee TXNDC17 (100% identical), macaque TXNDC17 (99% identical), guinea pig TXNDC17 (89% identical), pig TXNDC17 (89% identical), mouse Txndc17 (80% identical), rat Txndc17 (80% identical), zebrafish txndc17 (69% identical), dog TXNDC17 (65% identical), Caenorhabditis elegans txdc-17 (41% identical), Drosophila melanogaster cl (38% identical), Drosophila melanogaster CG3939 (33% identical).
Diseases named in the same sentence as TXNDC17 in open-access papers:
TXNDC17 is named in the same sentence as 13 diseases in open-access papers, as found by Europe PMC text mining. Sharing a sentence is not in itself a finding about the gene and the disease. The quoted sentences say what the papers report.
ovarian carcinoma (9 papers, 2016 to 2024). A malignant neoplasm originating from the surface ovarian epithelium. "Studies have shown that up-regulation of autophagy acts as a promoter of paclitaxel resistance in ovarian cancer induced by the high expression of the autophagy-associated gene TXNDC17." (PMID 39695078, 2024). "Resistance linked to paclitaxel, the first-line chemotherapy against ovarian cancer, appears to be related to increased levels of thioredoxin domain-containing protein 17 (TXNDC17), a ubiquitous cytosolic protein that acts as a chemoresistant promoter and activates cytoprotective autophagy." (PMID 33233671, 2020). "For instance, the reported research showed that TXNDC17 promoted paclitaxel resistance via inducing autophagy in ovarian cancer." (PMID 36747547, 2023). "Thioredoxin domain‐containing 17 (TXNDC17) promotes paclitaxel resistance by inducing autophagy in ovarian cancer." (PMID 35075807, 2022). "The up-regulation of autophagy which was induced by thioredoxin domain containing 17 (TXNDC17) promoted paclitaxel resistance in ovarian cancer." (PMID 27825125, 2016). "Moreover, TXNDC17 promotes tumor resistance to paclitaxel in ovarian cancer by regulating BECN1‐mediated autophagy, and high TXNDC17 expression has been confirmed to be associated with poor prognosis in patients with ovarian cancer." (PMID 39411839, 2024). "TXNDC17 is involved in chemotherapy resistance of ovarian cancer." (PMID 37686174, 2023). "PTX induces upregulation of thioredoxin domain containing 17 (TXNDC17) and autophagy through Beclin-1 participation, which consequently results in PTX resistance in ovarian cancer." (PMID 36359776, 2022).
colorectal cancer (4 papers, 2016 to 2021). A primary or metastatic malignant neoplasm that affects the colon or rectum. "Interestingly, the expression of TXNDC17 has been recently associated with paclitaxel resistance in ovarian and colorectal cancer." (PMID 33806075, 2021). "Another example is the thioredoxin domain containing 17 (TXNDC17), also known as Trx-related protein of 14 kDa (TRP14), which is STAT-3-dependent and responsible for the drug resistance in human colorectal cancer cells." (PMID 27872753, 2016).
acute pancreatitis (1 paper, 2024). An acute inflammatory process that leads to necrosis of the pancreatic parenchyma. "Txndc17 knockout mice were, surprisingly, protected in an acute pancreatitis model, concomitant with activation of Nrf2-driven antioxidant pathways and upregulation of transsulfuration." (PMID 38811853, 2024).
breast tumors (1 paper, 2023). "We obtained 5 prognosis-related genes, as the key biomarkers by Lasso-cox analysis (FBXL19, HAGHL, PHKG2, PKMYT1, and TXNDC17), all of which were significantly upregulated in breast tumors." (PMID 36747547, 2023).
lung carcinoma (1 paper, 2020). "Through our analysis, we also found other eight proteins (ACAT2, PSIP1, TCERG1, DPYSL5, TUBA1A, AKR1B1, ANP32E, and TXNDC17) that have been associated with other cancers, but not in lung cancer." (PMID 32351780, 2020).
cancer (2 papers, 2020 to 2023). A tumor composed of atypical neoplastic, often pleomorphic cells that invade other tissues. "A few of researches shown that TXNDC17 promoted the growth and development of cancer cells by regulating the autophagy signal pathway." (PMID 36747547, 2023). "The research closely interrelated to TXNDC17 in cancer was rare." (PMID 36747547, 2023). "The result showed that HAGAL and TXNDC17 were lowly expressed in cancer." (PMID 36747547, 2023).
TXNDC17 also shares sentences with these, for which no sentence is quoted: tumor (4 papers); infection (2); breast carcinoma (1); cervical cancer (1); Hyperglycemia (1); oral disease (1); pancreatitis (1).